RAB35 (RAB35, member RAS oncogene family)
Diseases named in the same sentence as RAB35 in open-access papers (continued):
Sharing a sentence is not in itself a finding about the gene and the disease.
glioblastoma (2 papers, 2022 to 2024). The most malignant astrocytic tumor (WHO grade IV). "Rab35 is required during neuronal development in the hippocampus, its expression is decreased in glioblastoma, and disruption of Rab35 enhances growth and invasiveness of human glioblastoma in mouse xenograft models." (PMID 38432637, 2024). "Altered Rab35 function contributes to progression of glioblastoma, defects in primary cilia formation, and altered cytokinesis." (PMID 38432637, 2024). "When assessing the expression of RAB27B, RAB11 and RAB35, which may be the main potential actors of such a compensation, the only protein exhibiting an enhancement was RAB27B in the glioblastoma model." (PMID 35216426, 2022).
ovarian carcinoma (2 papers, 2009 to 2018). A malignant neoplasm originating from the surface ovarian epithelium. "Rab35 was chosen as it was the most highly upregulated gene in the cDNA microarray experiment, and Rab25 was chosen as this protein has been linked with ovarian cancer." (PMID 19623182, 2009). "Finally, the clinical significance of this upregulation was investigated by examining the expression of Rab25 and Rab35, two G-protein-related molecules in an ovarian cancer tissue microarray (TMA)." (PMID 19623182, 2009). "Further work is required to investigate the functional role of Rab35 in ovarian cancer, but this gene may have use as a biomarker of AR function in ovarian cancer, thus being able to predict those patients who are likely to respond to antiandrogen therapy." (PMID 19623182, 2009).
amyloid (1 paper, 2021). "Importantly, Rab35 overexpression protects against this GC-driven interaction, supporting the concept that Rab35 downregulation is a precipitating factor in stress/GC-induced amyloid pathology." (PMID 34876559, 2021).
Anxiety (1 paper, 2023). Intense feelings of nervousness, tension, or panic often arise in response to interpersonal stresses. "Since RAB35 is also expressed in other brain regions, including the striatum and prefrontal cortex, the loss of RAB35 in such regions may contribute to reduced anxiety-related behaviors in Rab35 cKO mice." (PMID 37085665, 2023). "Behavioral tests revealed that CNS-specific Rab35 cKO mice have defects in a broad range of behaviors, such as anxiety-related behaviors and motor function, as well as spatial memory." (PMID 37085665, 2023). "In the open field test, which measures spontaneous motor activity and anxiety-related behavior in a novel environment, Rab35 cKO mice exhibited spontaneous movement with travel times similar to the control mice, indicating that their horizontal locomotor activities were comparable." (PMID 37085665, 2023). "Taken together, these results suggest that RAB35 deficiency does not affect horizontal locomotor activity but causes defects in anxiety-related behaviors and motor function." (PMID 37085665, 2023). "Our data suggest that disrupted layer formation in the ventral hippocampus of Rab35 cKO mice may affect anxiety-like behaviors." (PMID 37085665, 2023). "In addition, Rab35-knockout mice exhibited defects in spatial memory and anxiety-related behaviors." (PMID 37085665, 2023). "Although 13 of the 22 Rab35 cKO mice dropped from the open arms during the test, we evaluated the anxiety levels of nine mice that completed the test without falling." (PMID 37085665, 2023).
astrocytoma (1 paper, 2023).
Atrophy (1 paper, 2021). Any weakening or degeneration, especially through lack of use. "Importantly, high GC suppress Rab35 transcription resulting in Tau accumulation due to its impaired degradation while overexpression of Rab35 reverses GC-induced Tau accumulation and related neuronal atrophy in the hippocampus." (PMID 34366802, 2021).
cataract (1 paper, 2020). Partial or complete opacity of the crystalline lens of one or both eyes that decreases visual acuity and eventually results in blindness. "In mice, loss of Rab35 is lethal, and Rab35 heterozygous mutants display defects in lens formation and develop cataracts." (PMID 32033485, 2020).
childhood asthma (1 paper, 2022). "The gene DENND1B encodes the guanine nucleotide exchange factor (GEF) for RAB35 that acts as a regulator of T-cell receptor (TCR) internalization in TH2 cells which functions as a regulator in the process of childhood asthma." (PMID 35198010, 2022).
ciliopathy (1 paper, 2024). A genetic disorder of the cellular cilia or the cilia anchoring structures, the basal bodies, or of ciliary function.
co-infection (1 paper, 2025). "To test this hypothesis, we transfected HeLa cells with GFP-tagged Rab14 and Rab35 and used our Inc co-infection model to evaluate Inc and Rab binding to CpoS." (PMID 41251378, 2025).
colon cancer (1 paper, 2023). "To determine if this localization is evolutionarily conserved, we examined the spatial localization of miR-31 and its targets Fascin and Rab35 in HCT116 (human colon cancer cells), which is known to have upregulated miR-3129." (PMID 37398341, 2023).
cystitis (1 paper, 2015). Inflammation of the urinary bladder. "Mice were infected with a cystitis isolate of UPEC, and bladders were removed at 24 h and 2 week time points, fixed, sectioned, and stained for UPEC and Rab35." (PMID 26248231, 2015).
deafness (1 paper, 2018). An inherited or acquired condition characterized by the complete loss of the ability to hear from one or both ears. "A Mutation in the gene TBC1 Domain Family Member 24 (TBC1D24), encoding for a GTPase activating the proteins Rab5 and Rab35, involved in endosome to lysosome trafficking as a mechanism for degrading synaptic vesicles associated proteins, has been shown to cause severe neurodegeneration and deafness." (PMID 29760588, 2018).
gastrointestinal stromal tumor (1 paper, 2023). "USP32 promotes the exocrine secretion of imatinib-resistant gastrointestinal stromal tumors by decreasing the Lys48 (K48) ubiquitination of Rab35, protecting it from proteasome destruction." (PMID 37679322, 2023). "A recent study discovered and concluded that Rab35 can influence the spread of drug resistance by controlling the exocrine secretion of gastrointestinal stromal tumors, and that gastrointestinal stromal tumors considerably overexpressed Rab35." (PMID 37679322, 2023).
leukemia (1 paper, 2021). A malignant (clonal) hematologic disorder, involving hematopoietic stem cells and characterized by the presence of primitive or atypical myeloid or lymphoid cells in the bone marrow and the blood. "In a study related to leukemia, investigators found that RAB35 has a strong promoting effect on cancer cell invasion, metastasis and immune escape." (PMID 34500436, 2021).
mental disorder (1 paper, 2023). A disease that has its basis in the disruption of mental process. "Mutations in Rab35 cause various diseases, including mental disorders." (PMID 36253443, 2023).
neuroblastoma (1 paper, 2018). Neuroblastoma (NB) is the most common solid, extracranial childhood tumor. "In a neuroblastoma cell model, overexpression of RAB35 led to increased aggregation and secretion of α-synuclein A53T66." (PMID 30150626, 2018).
neuropathies (1 paper, 2020). "Our findings reveal a crucial role for Rab35-regulated lipid turnover by myotubularins in the control of mTORC1 activity and myelin growth suggesting possible avenues for the treatment of CMT 4B-type neuropathies in humans." (PMID 32503983, 2020). "Unlike its interaction partners MTMR13 or MTMR2 (bound to Rab35 via MTMR13 or MTMR5) Rab35 does not appear to be an inherited neuropathy disease gene." (PMID 32503983, 2020).
paraplegia (1 paper, 2014). Complete paralysis of the lower half of the body including both legs, often caused by damage to the spinal cord. "A further two Rabs showed strong and specific interactions with membrane traffic machinery that we did not validate because of a lack of suitable reagents: Rab26 with the spastic paraplegia proteins Spg11 and Spg15 (also found with Rab7), and Rab35 with the Rab GEF Sbf (SBF1/2 in humans)." (PMID 25453831, 2014).
parkinsonian disorder (1 paper, 2016). A group of disorders which feature impaired motor control characterized by bradykinesia, MUSCLE RIGIDITY; TREMOR; and postural instability. "Our results suggest that Rab35 is potentially useful in the differential diagnosis of parkinsonian disorders and is implicated in the pathogenesis of PD." (PMID 27509057, 2016). "It suggests that the change of Rab35 protein is specific for PD and there are different pathogenic mechanisms involved in these parkinsonian disorders." (PMID 27509057, 2016).
prostate carcinoma (1 paper, 2018). A carcinoma that arises from epithelial cells of the prostate gland. "Of note, the analysis of the TCGA data set indicated that RAB35 display a significant elevated copy number variation in about 16% of human prostate cancers." (PMID 29662076, 2018). "In addition, there is a correlation between the levels of RAB35 and of phosphoAKT in prostate cancer cell lines." (PMID 29662076, 2018). "The variable expression of RAB35 was also observed across a panel of human prostate cancer in a Tissue Microarray (TMA) with 12/56 (21.4%) adenocarcinoma displaying elevated levels of RAB35 (score ≥ 1.5), whereas only 2/32 (6%) of normal prostate tissues displayed RAB35 scores = 1.5." (PMID 29662076, 2018).
shigellosis (1 paper, 2012). Shigellosis is a bacterial infection leading to dysentery and is caused by Shigella, which are small, ubiquitous Gram-negative bacteria belonging to the enterobacteria family. "The best understood of these is the DENND1 subfamily, which has been shown to control Rab35 in an endocytic pathway required for yolk protein receptor recycling in C. elegans, MHC-I recycling in mammals, and the uptake of the causative agent of shigellosis – Shiga toxin." (PMID 22595670, 2012).
Tremor (1 paper, 2016). An unintentional, oscillating to-and-fro muscle movement about a joint axis. "To further investigate the characteristics of PD patients with a high level of Rab35 (Rab35 level >190 pg/ml in 25% of patients), we analyzed tremor-dominant phenotype, the levodopa equivalent daily dose, disease duration and onset age of disease in PD patients with a high level of Rab35." (PMID 27509057, 2016).
type 2 diabetes (1 paper, 2019). "RAB35, one of the key regulators of intracellular transport, was downregulated in our patients with type 2 diabetes after NPWT." (PMID 30221321, 2019).
cancer (17 papers, 2011 to 2025). A tumor composed of atypical neoplastic, often pleomorphic cells that invade other tissues. "Mutations in Rab35 that lead to a constitutively active form are associated with cancer development in human." (PMID 31527750, 2019). "Despite all the data available, the literature lacks information about the specific phenotypic differences that Rab11 and Rab35 confer to dividing cancer cells." (PMID 40877912, 2025). "Even though the functions of Rab35 in cell migration and adhesion vary according to cell types or migration assays, it emerges as a central component during cancer progression for receptor presentation, actin dynamics, and cell polarity." (PMID 33850145, 2021). "Although Rab35 are also reported, the function of Rab35-regulated exosomes in cancer remains unclear." (PMID 34141705, 2021). "Mechanistically better defined is podocalyxin’s sorting into cancer cell EVs, which is controlled by Rab35, and this influences ECM deposition in metastatic target organs by influencing Rab-coupling protein–dependent integrin trafficking machinery in fibroblasts." (PMID 34623384, 2021). "Furthermore, overexpression of related Rab proteins with overlapping functions does not rescue the cytokinetic defects caused by Rab11 or Rab35 downregulation in cancer cells." (PMID 40877912, 2025). "Since Rab11 and Rab35 play functionally similar roles during cell division, it would be interesting to see whether the individual or simultaneous downregulation of both, in terms of the regulation of cytokinesis, would have any effect on the progression of cancer cell division." (PMID 40877912, 2025). "Although some studies showed that RAB35 has the opposite effect on the migration in some kind of cancer cells, in the present work, we found that EGF induced RAB35 activation, while blocking RAB35 expression greatly abolished EGF-induced cell invasion." (PMID 27430308, 2016). "Despite a substantial body of research on each protein individually, no study to date has systematically compared Rab11 and Rab35 in the context of cancer cell division." (PMID 40877912, 2025). "Although in vitro GEF activity of folliculin for mammalian Rab35 has been detected, and folliculin was reported to activate Rab35 to mediate EGF receptor recycling in a cancer cell line, the functional relationship between folliculin and Rab35 in an animal context has not been reported." (PMID 30138370, 2018). "Therefore, it is not surprising that RAB35 can exert an important role in different types of cancer by controlling several aspects of cancer progression, such as cell migration, proliferation and survival." (PMID 38533085, 2024). "Rab35 is an endocytic/recycling Rab and the identified Rab35 mutants, by regulating endocytosis and recycling, contribute to growth factor-mediated activation of phosphatidylinositol 3-kinase (PI3K) and protein kinase B (AKT) thus promoting cancer cell survival." (PMID 31426400, 2019).
tumor (17 papers, 2009 to 2025). "And, these mutations and continuously activated Rab35Q67L mutation can inhibit apoptosis, suggesting that Rab35 is involved in EGFR-mediated tumor progression." (PMID 30524285, 2018). "More importantly, Rab35 somatic mutations (Rab35A146T and Rab35F156L) are found in various tumor cells of the uterus, lymph and lungs." (PMID 30524285, 2018). "Aberrant Rab35 expression and gene mutation are associated with malignance, however, the oncogenic as well as tumor suppressive function of Rab35 have been reported previously." (PMID 29018350, 2017). "Recently, another oncogenic Rab35 has been identified by two gain-of-function mutations in tumor cells." (PMID 27716280, 2016). "In GISTs, USP32 protects Ras-related protein Rab-35 (Rab35) from proteasomal degradation, leading to tumor resistance to Imatinib, a tyrosine kinase inhibitor that is wildly used to combat GISTs." (PMID 37957631, 2023). "RAB27A, RAB27B, and RAB35 are abnormally expressed in tumors and participate in the regulation of tumor exosome secretion." (PMID 34088337, 2021). "It is the upstream activation and recruitment that determines the diversity of Rab35 in regulating tumor progression." (PMID 30524285, 2018). "It has been shown that RAB35 functions as a tumor suppressor and attenuated signaling downstream of Arf6." (PMID 27430308, 2016). "Based upon these observations, it is important to further validate the functions of the miR-720/Rab35 axis in tumor metastasis and invasion in animal models and clinical tissues in future studies." (PMID 26413265, 2015). "Moreover, HSP70 protein expression was reduced in exosomes secreted by tumor cells transfected with miR-185-5p mimic or RAB35 siRNA." (PMID 34500436, 2021). "Then, we found that the expression of RAB35 was higher in tumor tissues than in adjacent tissues." (PMID 34500436, 2021). "Therefore, our study of the upstream regulatory mechanism of Rab35 is a good complement to the role of Rab35 in tumor development." (PMID 30524285, 2018). "In lymphoma cells, Rab35 interacts with MPM-ALK to promote tumor progression." (PMID 30524285, 2018). "Notably, RAB35 has ample opportunities to influence diverse cell signaling, resulting in functional promiscuity on tumor initiation and progression, and the activity of RAB35 in tumor is of tremendous research interest." (PMID 27430308, 2016). "Additionally, exosomes derived from tumor cells restored cell proliferation, migration and invasion, whereas exosomes secreted by tumor cells with downregulation of RAB35 expression or overexpression of miR-185-5p lost their ability to restore cell proliferation, migration and invasion." (PMID 34500436, 2021). "Finally, tumor cell-derived exosomes with genetic downregulation of RAB35 or overexpression of miR-185-5p were co cultured with their parental cells to verify the regulatory role of RAB35 on exosome secretion and function." (PMID 34500436, 2021). "Thus, RAB35 might not only be important for the onset of tumorigenesis, but also to increase nutritional tumour adaptation and progression, possibly by promoting tumour dissemination potential." (PMID 29662076, 2018). "When overexpressing miR-185-5p or interfering with RAB35, we observed suppressed TSG101 protein and CD63 protein expression in tumor cells and their derived exosomes." (PMID 34500436, 2021).
tumor (continued). "For example, MES GBMs (red arrows) were enriched for CAV1, CD44, CD63, RAB27A, SDCBP and SMPDL3A, while PN (blue arrows) tumours contained higher levels of transcripts for ANXA6, CD81, hnRNPA2B1, YBX1 (RNA binding proteins) and RAB35." (PMID 30034643, 2018). "In colon cancer cells, ACAP2, a downstream effector of Rab35, and also GTPase activating proteins (GAP) of ARF6, inhibits ARF6 and thus inhibits epithelial-mesenchymal transition (EMT) of tumor cells." (PMID 30524285, 2018). "Tumor growth was not impaired with Rab27a or Rab35 KO cells, and overall cell proliferation, as stained for by Ki-67 was unchanged." (PMID 41137505, 2025). "We have not shown any clinical significance related to Rab35 expression, although 95% of the tumours examined showed expression of the protein." (PMID 19623182, 2009).